SPOP (speckle type BTB/POZ protein)
Diseases named in the same sentence as SPOP in open-access papers (continued):
Sharing a sentence is not in itself a finding about the gene and the disease.
tumor (195 papers, 2013 to 2026). "Loss-of-function mutations in SPOP compromise ubiquitination-mediated PD-L1 degradation, leading to increased PD-L1 levels and reduced tumor-infiltrating lymphocytes." (PMID 39851497, 2025). "The speckle type BTB/POZ protein gene (SPOP) is a frequently mutated gene in PCa that serves as a crucial tumor suppressor by functioning as a ubiquitin ligase, mediating the intracellular degradation of AR." (PMID 41247636, 2025). "This compromised NE was more vulnerable to damage from farnesyltransferase inhibitors (FTIs), causing nuclear rupture in SPOP-mutant tumor cells." (PMID 40662365, 2025). "Functional analyses revealed that low SPOP expression was associated with disrupted immune regulation and altered metabolic pathways, potentially driving tumor progression." (PMID 40657370, 2025). "Loss of SPOP suppresses B16 tumor growth in a manner dependent on host immunity and tumor-intrinsic STING." (PMID 41148213, 2025). "High SPOP expression was also associated with cellular differentiation and quiescence, further supporting its role in tumor suppression." (PMID 40657370, 2025). "Increasing studies uncovered that tumor-derived SPOP mutations disrupt SPOP interacting with substrates, preventing their degradation." (PMID 38409107, 2024). "Another evidence of a tight link between SPOP and tumorigenesis comes from its high frequency of mutation in human tumor samples." (PMID 38409107, 2024). "SPOP, a tumor suppressor frequently mutated in cancers, was also upregulated and has been implicated in senescence induction and myofibroblast activation." (PMID 40692702, 2024). "SPOP-M35L promotes HCC cell proliferation and metastasis, suggesting that M35L mutation possibly reprograms SPOP from a tumor suppressor to an oncoprotein." (PMID 38409107, 2024). "Established early oncogenic driver alterations including ERG gene fusions as well as FOXA1, CDK12, and SPOP mutations were typically present in both the primary tumor and LN metastatic foci." (PMID 38773085, 2024). "Functionally, SPOP enables inhibition of the anti-tumor role of IRF2BP2 in HCC cells, which is eliminated by mutating the SBC motif in IRF2BP2." (PMID 38409107, 2024). "Patients with CC tumours are more likely to have deletions at specific chromosomal sites (6q, 8p and 10q) and increased SPOP and ATM mutations." (PMID 39022662, 2024). "For example, mutations in the SPOP gene lead to increased stability of tumor-associated proteins like PTEN and enzymes involved in the PI3K/mTOR signaling pathway, enhancing cell proliferation." (PMID 39296545, 2024). "Recently, SPOP mutations were revealed to enhance tumor immune escape through targeting the interferin regulatory factor 1 (IRF1)-PD-L1 axis in endometrial cancer." (PMID 36733484, 2023). "While our study concurs with BRCA2-/- in hyper-deleted tumours (3/5), here we report further association with SPOP mutation." (PMID 36045381, 2022). "Differential expression levels or mutation profiles of SPOP in tumours play different roles in tumorigenesis and cancer progression." (PMID 36474188, 2022). "In PCa, SPOP was identified as a tumor suppressor, and SPOP was associated with the ERG protein stability and the growth and aggressiveness of PCa." (PMID 36275733, 2022). "Because of the difficulty in extracting sufficient quality genomic DNA from very small tumor foci, we were limited in our ability to characterize all tumor foci SPOP mutation status." (PMID 35050902, 2022). "We observed that SPOP deficiency notably promoted DLBCL tumor growth in mice compared with tumors derived from parental OCI-Ly7 cells." (PMID 35773729, 2022). "They indicated that SPOP played a tumor-promoting role, and higher SPOP expression was associated with worse clinical stage." (PMID 34838022, 2021). "Based on the tumor-suppressive role of SPOP in PCa and the results of loss-of-function assays, SPOP mutations are expected to include the invasion and proliferation of PCa cells." (PMID 33708770, 2021).
tumor (continued). "Given the notion that wild type SPOP dampens AR function in the context of ERG to sustain tumor growth, we asked if VCaP cells are particularly susceptible to increased DHT levels." (PMID 33531470, 2021). "Speckle-type pox virus and zinc finger protein (SPOP) missense mutations resulting in functional loss of this tumour suppressor occurs in approximately 10–15% of PCa." (PMID 34128831, 2021). "While mutant SPOP renders tumor cells susceptible to androgen deprivation therapies, ERG promotes sensitivity to high-dose androgen therapy and pharmacological inhibition of wild type SPOP." (PMID 33531470, 2021). "In contrast, in the case of TSGs (i.e., CDKN2A, CTNNB1, and SPOP), MSCs were small and the differences between “mutation-tumor type” combinations are also small." (PMID 34424899, 2021). "Conversely, we show that the ERG oncogene’s presence increases the susceptibility of tumor cells to high-dose androgen therapy, while cells expressing mutant SPOP remain largely unaffected." (PMID 33531470, 2021). "Conversely, tumor-associated SPOP mutations disrupted LLPS and SPOP-substrate accumulation, thus inhibiting ubiquitin-dependent proteolysis of downstream proteins." (PMID 31901237, 2020). "Consistently, low expression of ZBTB38 is correlated with the same integrative Cluster 1 (p < 0.00001), DNA methylation cluster 2 (p < 0.00001) and mRNA cluster 1 (p < 0.00001) as SPOP mutation molecular subgroup of tumours." (PMID 32365491, 2020). "SPOP mutations in PCa are significantly associated with increased PCa cell proliferation and invasion, indicating the loss of function of SPOP mutations and the tumor-suppressive role of SPOP in PCa." (PMID 33281882, 2020). "Together, we think that either alteration of SPOP via mutations or low expression reduces SPOP’s tumor suppressive impacts." (PMID 31772275, 2020). "Expression of these SPOP mutants, thus, causes aberrant turnovers of the substrate proteins, leading to tumor formation." (PMID 33023230, 2020). "It is well-known that SPOP usually acts as a tumor suppressor in PCa and somatic missense mutations of SPOP occur frequently in PCa." (PMID 29262542, 2017). "Mutations in SPOP can lead to the loss or alteration of its function, which impacts substrate protein degradation and cellular biological processes, ultimately promoting tumor cell growth and metastasis." (PMID 40034124, 2025). "In addition, we constructed 3D patient tumor avatars derived from patients with PCa through 3D bioprinting, named 3D bioprinted PCa organoids (3DP-POs), to further confirm the sensitivity of SPOP-mutated PCa to olaparib." (PMID 40260915, 2025). "Moreover, in cell-derived xenograft (CDX) models, olaparib exhibited more pronounced inhibition of tumor growth in CDX models carrying SPOP mutations." (PMID 40260915, 2025). "Additionally, SPOP mutations have been implicated in tumor immune escape by regulating the IRF1-PD-L1 axis, further highlighting its critical role in immune modulation." (PMID 40657370, 2025). "While the pathological Ser40 mutation has not been identified in patient databases, these findings suggest that clinical SPOP mutations could lead to aberrant PrLZ accumulation, driving tumor progression and contributing to poor outcomes in PCa patients." (PMID 40521202, 2025). "Interestingly, among the 117 tumor tissues, we identified one sample with an SPOP mutation at F133V by NGS." (PMID 38632244, 2024). "However, exon sequencing reveals that tumor samples show high-frequency SPOP somatic mutations, which cluster in its MATH domain." (PMID 38409107, 2024). "Additionally, research has identified the mutation status of SPOP as an important independent prognostic marker for metastatic PCa, with SPOP mutations rendering tumor cells susceptible to androgen deprivation therapy." (PMID 39530098, 2024). "Results describing the frequency of SPOP mutations in both AA and EA tumor samples varied." (PMID 36937425, 2023).
tumor (continued). "In summary, aberrant accumulation of the PrLZ oncoprotein due to clinical SPOP mutation or abnormal activation of ERK1/2 in PCa could be the underlying molecular mechanisms driving tumor progression and resulting in poor survival of PCa patients." (PMID 35194188, 2022). "SPOP deficiency mainly depended on CHAF1A to accelerate in vivo DLBCL tumor growth." (PMID 35773729, 2022). "Furthermore, PrLZ significantly promoted the growth of SPOP F102C mutation xenografts and SPOP WT impeded PrLZ-mediated pro-tumor effects in vivo." (PMID 35194188, 2022). "In contrast, tumor-associated SPOP mutations may disrupt LLPS and thereby inhibit the ubiquitin-dependent proteolysis of substrates." (PMID 36360288, 2022). "Three somatic SPOP missense mutations were identified in 16 out of the 198 tumor tissues (8%)." (PMID 34322378, 2021). "Our results reveal a tumor suppressor role of SPOP in preventing DNA replication over-firing and genome instability and suggest that SPOP-mutated tumors may be susceptible to ATR inhibitor therapy." (PMID 34599168, 2021). "Tumor-associated missense mutations in the substrate recognition domain of SPOP disrupt substrate binding and ubiquitination, leading to the accumulation of oncogenic substrates, such as steroid receptor coactivator (SRC3), c-MYC and death-domain-associated protein (DAXX)." (PMID 33138914, 2020). "To investigate this hypothesis we searched for SPOP mutations in our high and low inflammation tumor cohorts." (PMID 26863016, 2016). "Furthermore, wild-type SPOP suppressed HepG2 cell migration, while SPOP-M35L enhanced cell migration, together suggesting that M35L mutation likely reprograms SPOP from a tumor antagonist to a tumor promotor via substrate selection." (PMID 38409107, 2024). "We next sought to test whether tumor-derived mutations affect SPOP interactions with IRF2BP2." (PMID 38409107, 2024). "SPOP expression and the association between its expression and patient prognosis and immune function were evaluated using The Cancer Genome Atlas (TCGA), Genotype-Tissue Expression (GTEx), The Tumor Immune Estimation Resource 2.0 (TIMER2.0) database, cBioportal, and various bioinformatic databases." (PMID 39074086, 2024). "Notably, many of these substrates have been linked to oncogenic processes, implying that SPOP might function as a tumor suppressor." (PMID 38632244, 2024). "However, targeting CHAF1A could abrogate the facilitative effect of SPOP loss on tumor growth, as indicated by tumor volumes and weight." (PMID 35773729, 2022). "However, several genomic analyses have provided evidence that SPOP is frequently mutated in human EC, indicating that wild-type SPOP may act as a tumor suppressor in this disease." (PMID 31901237, 2020). "Utilizing SPOP–/– MEF cell model, pancancer data analysis, and both in vivo and in vitro tumor models, this study elucidates the role of SPOP in regulating apoptosis and necroptosis and provides more insights for cancer targeted therapy." (PMID 41122967, 2025). "SPOP is a Cullin 3-based E3 ubiquitin ligase adaptor protein, and its multifunctionality in tumor biology has made it a prominent focus of cancer research 7-9." (PMID 40657370, 2025). "In theory, inducing apoptosis in tumors with abnormally high expression of SPOP can more easily kill tumor cells." (PMID 41122967, 2025). "The mRNA levels of RIPK3 displayed an expression trend opposite to that of SPOP across the tumor cell lines." (PMID 41122967, 2025).
tumor (continued). "After olaparib treatment, CDX models with SPOP knockdown and SPOP-F133L and SPOP-3KR exhibited significant tumor regression, suggesting sensitivity to olaparib treatment." (PMID 40260915, 2025). "Bioluminescence imaging revealed that the overexpressed SPOP group exhibited weak signals, whereas stronger and more extensive tumor cell metastasis signals were detected in the SPOP‐downregulated group." (PMID 41082269, 2025). "Based on this, we developed a combination therapy of SM164 and sunitinib for tumor types with high expression of SPOP/RIPK1, and the efficacy was significantly better than that of sunitinib monotherapy." (PMID 41122967, 2025). "Recent studies have shown that high SPOP expression is negatively correlated with lymph node metastasis, poor histological differentiation, and tumor malignancy according to TNM staging." (PMID 40521202, 2025). "The results revealed that after olaparib treatment, tumor tissues from CDX models with SPOP knockdown and SPOP-F133L and SPOP-3KR exhibited a pronounced increase in DNA damage and apoptosis." (PMID 40260915, 2025). "Palbociclib, a CDK4/6 inhibitor, enhances SPOP degradation and improves anti-tumor immunity in in vivo models." (PMID 39851497, 2025). "In Ewing sarcoma, ceramide triggers cleavage of the intracellular domain of GPR64, which translocates to the nucleus and promotes ubiquitination of RIF1 through the Cullin3-RING E3 ligase complex and SPOP, driving tumor growth." (PMID 40370434, 2025). "Through this systematic approach, we aim to elucidate the potential role of SPOP in tumor immune regulation and evaluate its impact on the immune therapy response in LUAD patients." (PMID 40657370, 2025). "Based on this, we developed a combination therapy of SM164 and sunitinib for tumor types with high expression of SPOP/RIPK1." (PMID 41122967, 2025). "A paired analysis of tumor and adjacent normal tissues in TCGA revealed that SPOP expression remained significantly elevated in KIRC and LIHC and significantly decreased in LUSC and COAD." (PMID 41122967, 2025). "We found that SPOP interacts with β-catenin in CRC and that β-catenin, a key player in the Wnt signaling, is not only intimately linked to carcinogenesis, tumor progression, and metastasis, but also plays a significant role in ferroptosis." (PMID 41213915, 2025). "In KC, SPOP promotes tumor progression by enhancing proliferation, inhibiting apoptosis 31,94, and regulating H3K36me3 levels and Hippo signaling 95,96." (PMID 40521202, 2025). "Mutations in SPOP result in the stabilization of GLP and G9a, causing abnormal upregulation of global DNA hypermethylation in a subset of tumor suppressor genes, including FOXO3, GATA5, and NDRG166." (PMID 40521202, 2025). "Of particular note, SPOP exerts tumor-suppressive effects by inducing the ubiquitination and degradation of oncoproteins, including c-Myc, androgen receptor (AR), and estrogen receptor-α (ERα)." (PMID 40483310, 2025). "Another study revealed that exosomal miR-17-5p derived from tumor stem cells impairs tumor-suppressive immunity in CRC by interfering with SPOP and enhancing PD-L1 expression." (PMID 40410719, 2025). "An intact immune microenvironment is crucial for suppressing B16 tumor growth following SPOP depletion." (PMID 41148213, 2025). "SPOP facilitates tumorigenesis by targeting and promoting the degradation of tumor suppressors like LATS1, PTEN, SETD2, and others, thus disrupting important signaling pathways such as the Hippo, PI3K/Akt, and cell cycle regulation pathways." (PMID 40521202, 2025). "Results showed that differences in tumor weights among the sh-NC + EV, sh-SPOP + EV, and sh-SPOP+sh-LMNB2 + EV groups were significantly reduced with Atezolizumab treatment, indicating that elevated LMNB2 promotes tumor immune evasion." (PMID 40483310, 2025).
tumor (continued). "This study demonstrated that SPOP functions as a tumor suppressor in CRC and that SPOP inhibits the proliferation and metastasis of CRC cells and increases their sensitivity to ferroptosis." (PMID 41213915, 2025). "COP1 ubiquitinates FASN to prevent excessive lipid accumulation, while mutations in SPOP impair FASN degradation, promoting tumor growth." (PMID 40370434, 2025). "Low SPOP expression in LUAD is associated with impaired immune regulation, altered cellular processes, and metabolic pathways, potentially contributing to tumor progression." (PMID 40657370, 2025). "Reexpression of SPOP largely rescued tumor growth in C57BL/6 mice, ruling out shRNA off-target effects." (PMID 41148213, 2025). "Consistently, SPOP inhibition synergized with anti–PD-1 therapy to suppress tumor growth via enhanced CD4+IFN-γ+ T cell infiltration and further boosted CAR.CD19-T efficacy in B16-OVA tumors." (PMID 41148213, 2025). "For example, in SPOP‐mutant PCa, SPOP loss (F102C/F133V) leads to STING protein stabilisation and accumulation, preferentially activating the NC‐STING–NF‐κB pathway, thereby promoting tumour growth." (PMID 41275427, 2025). "SPOP has been recognized as a critical tumor suppressor in various malignancies, including those of the digestive system." (PMID 40521202, 2025). "While SPOP’s regulation of intrinsic cellular programs is well documented, its role in immunity and the tumor microenvironment is less clear." (PMID 41148213, 2025). "Through these actions, SPOP enhances cell proliferation, invasion, and survival, contributing to tumor growth and metastasis." (PMID 40521202, 2025). "Tumor stage pT3 was statistically related to PTEN and SPOP loss of expression (p = 0.012 and p = 0.011), as well as to ERG overexpression and the “triple hit” phenotype (p = 0.051 and p < 0.001)." (PMID 38017230, 2024). "Studies show that speckle-type POZ protein (SPOP) reduces tumor growth and increases apoptosis in CRC, partly by ubiquitinating and degrading GLI2." (PMID 39184804, 2024). "Other AR-related genes (FOXA1, NCOA2, SPOP) exhibited minimal differences in transcript expression in either metastatic site relative to the primary tumor." (PMID 39349591, 2024). "Mechanically, circSLCO1B3 not only promoted ICC proliferation and metastasis via miR-502-5p/HOXC8/SMAD3 axis, but also eradicated anti-tumor immunity via suppressing ubiquitin-proteasome-dependent degradation of PD-L1 by E3 ubiquitin ligase SPOP." (PMID 38641828, 2024). "The positive correlations were detected between SPOP expression and infiltration levels of CD4+ T cells and CD8+ T cells, implying the key role of SPOP in regulating tumor immunology." (PMID 39074086, 2024). "Since SPOP plays a significant role in tumor infiltration, the correlation between genetic stability in human tumor samples and SPOP should also be taken into account." (PMID 39074086, 2024). "In PCa cells, unmutated SPOP promotes the degradation of full-length wild-type AR (AR-WT), and acts as a tumor suppressor." (PMID 37847340, 2024). "Ubiquitination and the SPOP E3 Ub ligase play important roles in tumor development, by regulating the cell cycle." (PMID 37847340, 2024). "Parallel IHC with a specific antibody for BRD4, a well-known SPOP substrate, displayed similar increased patterns in tumor tissues." (PMID 38632244, 2024). "SPOP is an E3 ubiquitin ligase adapter that acts as a tumor suppressor and has been found to exert an important role in CRC progression via mesenchymal–epithelial transition and matrix metalloproteinases." (PMID 39412096, 2024). "Current evidence supports the role of BCLAF1 as an oncogenic protein in HCC, whereas SPOP has been reported as an tumor suppressor in HCC." (PMID 38340178, 2024). "Speckle Type POZ Protein (SPOP), despite its tumor type-dependent role in tumorigenesis, primarily as a tumor suppressor gene is associated with a variety of different cancers." (PMID 39074086, 2024).